TRGV2 (T cell receptor gamma variable 2)
Description:
V region of the variable domain of T cell receptor (TR) gamma chain that participates in the antigen recognition. Gamma-delta TRs recognize a variety of self and foreign non-peptide antigens frequently expressed at the epithelial boundaries between the host and external environment, including endogenous lipids presented by MH-like protein CD1D and phosphoantigens presented by butyrophilin-like molecule BTN3A1. Upon antigen recognition induces rapid, innate-like immune responses involved in pathogen clearance and tissue repair. Binding of gamma-delta TR complex to antigen triggers phosphorylation of immunoreceptor tyrosine-based activation motifs (ITAMs) in the CD3 chains by the LCK and FYN kinases, allowing the recruitment, phosphorylation, and activation of ZAP70 that facilitates phosphorylation of the scaffolding proteins LCP2 and LAT. This lead to the formation of a supramolecular signalosome that recruits the phospholipase PLCG1, resulting in calcium mobilization and ERK activation, ultimately leading to T cell expansion and differentiation into effector cells. Gamma-delta TRs are produced through somatic rearrangement of a limited repertoire of variable (V), diversity (D), and joining (J) genes. The potential diversity of gamma-delta TRs is conferred by the unique ability to rearrange (D) genes in tandem and to utilize all three reading frames. The combinatorial diversity is considerably increased by the sequence exonuclease trimming and random nucleotide (N) region additions which occur during the V-(D)-J rearrangements.
Synonyms: TCRGV2; VIS2
Gene: T-cell receptor variable (V) gene on chromosome 7 (38,362,864 to 38,363,518, reverse strand). Ensembl gene ENSG00000233306.
Subcellular location: Cell membrane
Gene Ontology:
Cellular component: plasma membrane
Homologues: Orthologues: mouse Trgv7 (45% identical). Paralogues in human: TRGV4 (92% identical), TRGV5 (77% identical), TRGV1 (75% identical), TRGV3 (75% identical), TRGV8 (75% identical), TRGV10 (24% identical), TRGV11 (24% identical), TRGV9 (23% identical), TRGC1 (0% identical), TRGC2 (0% identical).
Diseases named in the same sentence as TRGV2 in open-access papers:
TRGV2 is named in the same sentence as 6 diseases in open-access papers, as found by Europe PMC text mining. Sharing a sentence is not in itself a finding about the gene and the disease. The quoted sentences say what the papers report.
tumor (3 papers, 2022 to 2023). "Among the upregulated genes, 5830411N06Rik (SCART2), Tcrg-C2, and Trgv2 were featured, indicating that Vγ4+ cells were more abundant in the lungs of tumor-bearing mice than tumor-free mice, which was also noted by flow cytometry." (PMID 36480166, 2023).
TRGV2 also shares sentences with these, for which no sentence is quoted: Ataxia (1 paper); neuropathy (1); prostate tumors (1); psoriasis (1); retinitis pigmentosa (1).